ACE (angiotensin I converting enzyme)
Diseases named in the same sentence as ACE in open-access papers (continued):
Sharing a sentence is not in itself a finding about the gene and the disease.
type 1 diabetes (37 papers, 2005 to 2025). "Currently however, the use of ACE inhibition in people with type 1 diabetes who are normotensive and normoalbuminuric cannot be recommended on the basis of trial evidence." (PMID 34979961, 2022). "With the data obtained in this study, we believe that ACE inhibitors, AT1 receptor blockers, or AT2 receptor agonists will become an essential target for treating type 1 diabetes and other diseases associated with hypercorticoidism in the future." (PMID 36465619, 2022). "Patients with type 1 diabetes were more likely using ACE inhibitors and/or ARBs as well as P2Y12 inhibitors." (PMID 36068573, 2022). "The following has been clearly shown in trials using angiotensin-converting-enzyme inhibitors (ACE inhibitors) for type 1 diabetes and angiotensin-II receptor blockers (ARBs) for type 2." (PMID 28197454, 2014). "Another consideration for the lack of a greater decline in aqueous flow than expected is the use of ACE inhibitors in all patients with type 1 diabetes in this study." (PMID 20573241, 2010). "A Canadian study evaluated the effect of provincial payment for ACE inhibitors in patients with type I diabetes with microalbuminuria." (PMID 18199282, 2008). "This study was performed to examine clinical and laboratory differences between adolescents with type 1 diabetes with and without microalbuminuria and the distribution of the ACE, AGTR1, and MTHFR gene polymorphisms." (PMID 39446857, 2024). "In a study with patients with type 1 diabetes, ACE inhibitor treatment increased serum ACE2 levels." (PMID 36899369, 2023). "In the early 1980s, aggressive blood pressure treatment was found to slow kidney function deterioration among individuals with type 1 diabetes, and subsequent findings a few years later proved the superiority of ACE inhibitors over other antihypertensive drugs." (PMID 38192517, 2023). "Additionally, prescription of ACE inhibitors reduces albuminuria and progressive kidney failure in type 1 diabetes and improves endothelial‐dependent function." (PMID 25428950, 2014). "It has been suggested that aldosterone escape during long-term RAAS blockade may be a mechanism by which ACE inhibition fails to prevent progressive renal disease in people with type 1 diabetes." (PMID 34979961, 2022). "A meta-analysis from 2001, spanning 12 studies with normotensive individuals with type 1 diabetes and moderate albuminuria, landed at an odds ratio of 3.07 for regression to normal AER in the ACE-inihibtor arm vs. placebo/nonintervention group." (PMID 38192517, 2023). "Treatment with empagliflozin attenuated hyperfiltration in 37 people with type I diabetes not on RAS inhibition and resulted in an increase in urinary levels of angiotensinogen, ACE, ACE-2, rise in plasma angiotensin I, II and renin activity as well as a fall in plasma ACE activity." (PMID 36247425, 2022).
Hyponatremia (36 papers, 2010 to 2025). An abnormally decreased sodium concentration in the blood. "Consistent with our findings, long-term use of angiotensin-II receptor antagonists and ACE inhibitors has been associated with hyponatremia in older people in Italy and Sweden." (PMID 40748456, 2025). "Associated risk factors for development of hyponatremia in this cohort were higher serum potassium and phosphate levels, lower serum magnesium concentrations as well as treatment with ACE inhibitors." (PMID 34578871, 2021). "Loop diuretics and ACE-inhibitors were only insignificantly associated with lower rates of hyponatremia." (PMID 31909095, 2020). "We present a patient with severe hyponatremia associated with lisinopril use and discuss the link between hyponatremia and ACE inhibitors." (PMID 32782860, 2020). "In the case of thiazides- and amiloride-induced hyponatremia and ACE-Is associated to hyponatremia, the proposed mechanism is increased ADH-secretion." (PMID 29804162, 2018). "To date, it has been reported that certain ACE inhibitors can cause hyponatremia, although the precise mechanism responsible remains to be elucidated." (PMID 22738362, 2012). "BB-induced suppression of ANG II and RAAS activity may blunt this signaling, predisposing patients to hyponatremia, fluid overload, or impaired hormonal feedback, especially when combined with diuretics or ACE inhibitors." (PMID 41463309, 2025). "The risk for hyponatremia increases when SSRI and SNRI are used in combination with angiotensin-converting enzyme (ACE) inhibitors, thiazide and thiazide-like diuretics, and proton pump inhibitors, inducing additive pharmacodynamic effects." (PMID 39558338, 2024). "In this study, only the coadministration of ACE‐i significantly increased the incidence of hyponatremia." (PMID 39623741, 2024). "Cumulative risks of hyponatraemia were frequently identified in patients receiving combination therapy with ACE inhibitors or sartans with aldosterone antagonists, diuretics, PPIs and SSRI/SSNRI or mirtazapine." (PMID 39770429, 2024). "Among these 7 patients affected by OD and hyponatremia, 5 (71.4%) were on ACE inhibitors, 2 on hydrochlorothiazide, and 1 on an antidepressant, all with potential side effects of hyponatremia and xerostomia." (PMID 34754078, 2021). "In our study, the use of ARB or ACEi was associated with hyponatremia after RAI therapy on univariate analysis, but when we performed multivariate analysis, the use of ARB or ACE inhibitors lost its statistical validity." (PMID 25170831, 2014). "In fact, the level of angiotensin I, but not angiotensin II, was remarkably high at the time when the first episode of hyponatremia developed on the 8th day of hospitalization, because the patient was treated with Enalapril, an ACE inhibitor." (PMID 22738362, 2012). "When combined with drugs that act on the RAAS, e.g., ACE inhibitors or diuretics; however, this suppression may increase the risk of hyperkalemia (especially in CKD), whereas hyponatremia is primarily associated with thiazide diuretics." (PMID 41463309, 2025). "Several of the medicines most commonly co-prescribed with thiazides among studies included in this meta-analysis, such as ACE inhibitors, AT1 receptor antagonists, NSAIDS and some anti-depressants, are associated with hyponatraemia through well-described mechanisms." (PMID 25139696, 2015). "Proton pump inhibitor (PPI) use, angiotensin-converting enzyme inhibitor/angiotensin receptor blocker (ACE/ARB) use, and spironolactone use (OR = 2.6 and 3.9, 2.3 with a p=0.02, 0.03, and 0.05, respectively) were associated with increased odds of severe hyponatremia." (PMID 38187818, 2023). "For thiazide, PPI, SSRI, loop diuretics, and ACE inhibitors we could not confirm significantly higher rates of hyponatremia." (PMID 31909095, 2020). "An ACE inhibitor or ARB was ceased in 3 patients, 2 of whom no diagnosis was recorded and 1 of whom was thought to have hyponatraemia secondary to diuretics." (PMID 30522474, 2018).
acute respiratory distress syndrome (35 papers, 2005 to 2025). Progressive and life-threatening pulmonary distress in the absence of an underlying pulmonary condition, usually following major trauma or surgery. "A study on mouse models of acute respiratory distress syndrome showed that ACE-deficient mice exhibit less lung damage." (PMID 38275965, 2024). "Presence of ACE insertion/deletion (I/D) polymorphism is associated with susceptibility and is an independent risk factor for mortality in patients with acute respiratory distress syndrome (ARDS)." (PMID 32901433, 2021). "We searched electronic databases through October 2011 for the terms “angiotensin-converting enzyme gene”, “acute lung injury”, and “acute respiratory distress syndrome,” and reviewed all studies that reported the relationship of the I/D polymorphism in ACE with ALI/ARDS in humans." (PMID 22938636, 2012). "Moreover, the ACE D allele has been shown to be more prevalent in patients suffering from adult respiratory distress syndrome (ARDS) in a previous study." (PMID 15819995, 2005). "Several pulmonary diseases and their activity are associated with elevated levels of ACE gene activity, including sarcoidosis, hypoxic pulmonary hypertension, idiopathic pulmonary fibrosis, and acute respiratory distress syndrome (ARDS)." (PMID 39591276, 2024). "A previous meta-analysis reported a positive association between an insertion/deletion (I/D) polymorphism in the angiotensin-converting enzyme gene (ACE) and the risk of acute lung injury (ALI)/acute respiratory distress syndrome (ARDS)." (PMID 22938636, 2012). "Exposure to high oxygen levels reduces the expression of ACE in models of acute lung injury and acute respiratory distress syndrome." (PMID 40352610, 2025). "The ACE I/D allele polymorphism and mortality in ARDS (Acute Respiratory Distress Syndrome) cohorts have been linked in a number of studies and meta-analyses." (PMID 37153428, 2023). "In the LPS-induced acute respiratory distress syndrome rat model, for example, the ratio of ACE/ACE2 was increased in the bronchoalveolar lavage fluid, resulting in activation of the ACE/AT1R/Ang II pathway, and increased expression of inflammatory factors." (PMID 36482404, 2022). "The pulmonary and renal capillary beds hold the majority of endothelium-bound ACE and patients with acute respiratory distress syndrome (ARDS) have increasing ACE insufficiency with increased severity of lung injury." (PMID 30368243, 2018). "RAS peptide analysis in vasodilatory shock and acute respiratory distress syndrome have strongly suggested a state of reduced angiotensin converting enzyme (ACE) and ACE2 function, respectively, which influences both the traditional and counter-regulatory axes of the RAS." (PMID 34391450, 2021). "Furthermore, the ACE D/D gene polymorphism causes the progression of pulmonary edema through increased microvascular permeability, which further worsens the clinical course and prognosis of the acute respiratory distress syndrome (ARDS) and has been linked to a high mortality rate in SARS patients." (PMID 36644496, 2023). "In patients with acute respiratory distress syndrome (ARDS), increased ACE levels in bronchoalveolar fluids are found, reflecting endothelial damage." (PMID 36235741, 2022). "ACE2 regulates the angiotensinrenin system, counteracting the activity of the angiotensin-converting enzyme (ACE) and having a protective effect on acute respiratory distress syndrome (ARDS)." (PMID 33776561, 2021). "A number of works have shown that the ACE–angiotensin II type 1 receptor (AT1R) axis is a critical mediator in the inflammatory cascade and alveolar epithelial cell apoptosis associated with ventilator-induced lung injury and acute respiratory distress syndrome (ARDS)." (PMID 33102532, 2020).
acute respiratory distress syndrome (continued). "An animal model of the acute respiratory distress syndrome (ARDS) provoked by SARS-CoV and SARS-CoV-2 infection showed that down-regulation of ACE2 causes an imbalance of ACE/ACE2 activity and results in accumulation of angiotensin II and in an increase of the pro-inflammatory response." (PMID 34123972, 2021). "The hypothesis that the ACE2 arm of the RAAS system could be of benefit in lung disease derives from the observation that ACE and angiotensin II are upregulated in acute lung injury (ALI), pulmonary fibrosis, pulmonary hypertension, and acute respiratory distress syndrome (ARDS)." (PMID 33195436, 2020). "By operating on the ACE/Ang-II/AT1R axis, ACE2 modulates RAS and several pathological processes, including fibrosis, hypertension, cardiac dysfunction, and acute respiratory distress syndrome (ARDS)." (PMID 39040892, 2024).
liver fibrosis (35 papers, 2009 to 2025). "The investigation into circulating angiotensin-converting enzyme (ACE) levels in patients newly diagnosed with chronic hepatitis B (CHB) seeks to elucidate the association between liver fibrosis and serum ACE concentrations." (PMID 40870535, 2025). "It has been observed that CHB patients often exhibit elevated circulating ACE levels, particularly those with more advanced stages of liver fibrosis." (PMID 40870535, 2025). "After carvedilol treatment, the extent of liver fibrosis was attenuated, and the expression of ACE was decreased accordingly." (PMID 31828132, 2019). "In the present study, ACE expression was significantly higher in liver fibrosis model mice than in control mice." (PMID 31828132, 2019). "In the liver fibrosis following liver injury, ACE, and AT1R are markedly increased and are localized to areas of active fibrogenesis." (PMID 23762250, 2013). "The progression of congenital hepatic fibrosis is mediated through the increase of angiotensin-converting enzyme (ACE), ANGII, and TGF-β1." (PMID 22500179, 2012). "The objective of this study was to determine if angiotensin converting enzyme inhibitors (ACE-Is) attenuate liver fibrosis in coinfection." (PMID 23193466, 2012). "Several studies applied the method of ACE inhibition and showed that reducing Ang II formation could significantly ameliorate bile duct ligation or CCl4 induced liver fibrosis in rats." (PMID 36313326, 2022). "Therefore, angiotensin-converting enzyme (ACE) inhibitors or AT1 receptor antagonists attenuate experimental liver fibrosis." (PMID 27637026, 2016). "Studies have shown that ACE inhibitors and ARBs may have a protective effect on the liver by inhibiting the angiotensin-aldosterone system, reducing oxidative stress, and improving blood flow, which may help to slow the process of liver fibrosis." (PMID 40361747, 2025). "In addition, ACE inhibitors may be an alternative anti-angiogenic strategy in the treatment of liver fibrosis and HCCs, because angiogenesis is an essential process in tumor growth and liver fibrosis." (PMID 37835456, 2023). "Modulation of other RAAS components (inhibition of ACE/Ang II/AT1R and stimulation of ACE2/Ang 1–7/Mas signaling pathways) was also shown to reduce hepatic fibrosis in a rodent model of hepatic fibrosis." (PMID 40872727, 2025). "ACE/AngII/AT1 axis inhibitors block AngII production and its effects, preventing the development of hepatic fibrosis and other liver diseases." (PMID 35629915, 2022). "Larger studies have shown similar favorable results in improving hepatic fibrosis, liver stiffness, and other markers of NAFLD after treatment with either angiotensin-converting enzyme (ACE) inhibitors or angiotensin receptor blockers (ARBs)." (PMID 36547416, 2022). "Studies in bile duct ligated (BDL) rats have shown that ARB, telmisartan decreased gene expression of ACE, AT1R, collagen type III, and TGF-β1 while increasing the expression of ACE2 and MasR with concomitant reduction in hepatic fibrosis." (PMID 33670126, 2021). "In rat models of CCL4-induced hepatic fibrosis and fructose fed-NAFLD, the hepatic RAS was over-activated and imbalanced, and the ratios of ACE/ACE2, AngII/Ang1-7, and AT1R/Mas were upregulated." (PMID 32322207, 2020). "Inhibition of angiotensin converting enzyme (ACE) and angiotensin II type 1 receptor (AT1) improves liver fibrosis by keeping HSCs in a quiescent state through suppression of TGF-β." (PMID 32650421, 2020). "Thus, the results indicate that ACE may be a promising biomarker for liver fibrosis." (PMID 31828132, 2019). "ACE and AT1R are reported to be highly expressed in activated human HSCs (hepatic stellate cells), which play a key role in liver fibrosis." (PMID 23762250, 2013). "Therefore, angiotensin-converting enzyme (ACE) inhibitors, as well as AT1-receptor blockers, have become promising pathological treatments for liver fibrosis." (PMID 36985782, 2023).
liver fibrosis (continued). "Combined with the GO, KEGG and Western blot results, COL1A2, ITGAV, TLR2, ACE, and PDGFRB may be potential targets for PE treatment of liver fibrosis." (PMID 36313326, 2022). "Angiotensin converting enzyme (ACE), a key enzyme of the classical RAS, converts angiotensin I (Ang I) to angiotensin II (Ang II), which acts via the Ang II type 1 receptor (AT1R) to stimulate hepatic fibrosis and increase intrahepatic vascular tone and portal pressure." (PMID 33670126, 2021). "Angiotensin-converting enzyme (ACE) and angiotensin II, as well as their downstream target, the profibrotic mediator TGF-β, are overexpressed in the PCK liver, suggesting that the renin-angiotensin system activation is another important mediator of hepatic fibrosis." (PMID 22007315, 2012). "More recently, researchers have shown that overexpression of ACE2, induced by ACE inhibitor (ACEI) activity and leading to the degradation of angiotensin (ANG) II into ANG 1-7, inhibition of autophagy and consequent HSC activation, might prevent liver fibrosis development." (PMID 41465213, 2025).
Allergy (34 papers, 2009 to 2025). An allergy is an immune response or reaction to substances that are usually not harmful. "Not only does this lead to a reduced potential to compensate and recover but also to the intake of medication such as ACE inhibitors or beta-blockers, which in turn are discussed as risk factors for severe allergic reactions." (PMID 31632639, 2019). "In a registry involving more than 5000 patients with acute allergic reactions, there was a higher risk of severe anaphylaxis in patients taking a beta-blocker and an ACE inhibitor concurrently than when a beta-blocker or an ACE inhibitor were given alone." (PMID 26525001, 2015). "Likewise, patients, especially those taking a beta blocker, or less often, angiotensin converting enzyme (ACE)-inhibitor, may be at a higher risk because of less response to epinephrine that might be needed to treat a systemic allergic reaction." (PMID 23369181, 2013). "All hypertensive patients were advised to take angiotensin receptor blockers (ARBs) or angiotensin converting enzyme inhibitors (ACE inhibitors) unless they had an allergy or intolerance to them." (PMID 33992075, 2021). "Another interesting aspect is the observation that drugs like beta-blockers, analgesics, and ACE inhibitors were reported as being cofactors for the development of severe allergic reactions." (PMID 30402598, 2017). "The CARE rule only looks for one contraindication to the use of an ACE Inhibitor: an allergy to this class of drugs." (PMID 24720863, 2014). "Rates of allergy/intolerance to medications in the most recent study year (2004) were as follows: ACE inhibitors/ARB’s 3.3%, aspirin 4.0%, aldosterone antagonists 0.1%, beta blockers 0.8%, and lipid-lowering medications 0.9%." (PMID 23671545, 2013). "The influences of ACE inhibitors and selected potential confounding variables (sex, age, previous SARS-CoV-2 infection, and allergy history) were evaluated by fitting univariate and multivariable Poisson regression models." (PMID 34579248, 2021). "Chao1, ACE, and Shannon of ileum in the FOS and allergy groups were significantly higher compared with the control group (p < 0.05)." (PMID 30524396, 2018).